LRGUK (leucine rich repeats and guanylate kinase domain containing)
Description:
Involved in multiple aspects of sperm assembly including acrosome attachment, shaping of the sperm head and in the early aspects of axoneme development. Not essential for primary cilium biogenesis.
Synonyms: FLJ32786; CFAP246
Tractability: No criterion of Open Targets' tractability assessment is met for any kind of drug.
Gene: Protein-coding gene on chromosome 7 (134,127,299 to 134,264,595, forward strand). Ensembl gene ENSG00000155530.
Subcellular location: Cytoplasmic vesicle, secretory vesicle, acrosome; Cytoplasm, cytoskeleton; Cytoplasm, cytoskeleton, cilium basal body
Gene Ontology:
Molecular function: protein binding
Biological process: axoneme assembly; spermatogenesis
Cellular component: acrosomal vesicle; cytosol; manchette; cytoskeleton
Genetic constraint (gnomAD): Loss-of-function variants: 30 observed, 36.16 expected, observed/expected ratio (o/e) 0.83, 90% interval 0.62 to 1.12. The upper end of that interval is the gene's LOEUF score, 1.12, which puts it in group 4 of 6, group 1 being the genes least tolerant of losing a copy. Missense variants: 461 observed, 454.87 expected, observed/expected ratio (o/e) 1.01, 90% interval 0.94 to 1.1. Synonymous variants: 178 observed, 176.72 expected, observed/expected ratio (o/e) 1.01, 90% interval 0.89 to 1.14.
Homologues: Orthologues: chimpanzee LRGUK (99% identical), macaque LRGUK (87% identical), dog LRGUK (77% identical), pig LRGUK (74% identical), guinea pig LRGUK (69% identical), rabbit LRGUK (68% identical), rat Lrguk (65% identical), mouse Lrguk (64% identical), tropical clawed frog lrguk (48% identical), zebrafish lrguk (40% identical), Drosophila melanogaster TbCMF46 (9% identical), Drosophila melanogaster Ppr-Y (8% identical). Paralogues in human: LRRC9 (17% identical), LRRCC1 (13% identical), DNAAF1 (12% identical), LRRC49 (12% identical), CEP97 (11% identical), DRC3 (11% identical), LRRC43 (10% identical), DNAAF11 (10% identical), LRRIQ3 (9% identical), PPP1R42 (8% identical), LRRC23 (8% identical), LRRC46 (8% identical), and 1 more.
Diseases named in the same sentence as LRGUK in open-access papers:
LRGUK is named in the same sentence as 8 diseases in open-access papers, as found by Europe PMC text mining. Sharing a sentence is not in itself a finding about the gene and the disease. The quoted sentences say what the papers report.
Ciliary Dyskinesia (2 papers, 2022 to 2024). "LRGUK and RSPH6A genes are implicated earlier only in mice models, while the ARMC4 gene is implicated in chronic destructive airway diseases due to primary ciliary dyskinesia." (PMID 38884051, 2024). "Notably, genes like LRGUK and RSPH6A were previously implicated only in mice models, while the ARMC4 gene was implicated in chronic destructive airway diseases due to primary ciliary dyskinesia." (PMID 38884051, 2024).
diabetes (2 papers, 2008 to 2020). "Association analyses to diabetes using SNPs in the EXOC4 and LRGUK gene regions identified multiple polymorphisms with evidence for association." (PMID 18498660, 2008). "Genes LRGUK and EXOC4 in ROH island on CHA14 are associated with diabetes and fasting glucose in human, and could be associated with endurance in this dog breed as it was shown that fasting glucose is significantly correlated with the intensity of the training regimen in professional athletes." (PMID 33139624, 2020).
male infertility (2 papers, 2024 to 2025). The inability of the male to effect fertilization of an ovum after a specified period of unprotected intercourse. "Four recessive (TRIOBP, SLC26A4, GJB2, COL4A3) and one dominant (SOX10) for the deafness; six recessive genes (LRGUK, DNAH9, ARMC4, DNAH2, RSPH6A, and ACE) for male infertility can be conclusively ascribed." (PMID 38884051, 2024).
Type 2 Diabetes (2 papers, 2008 to 2016). "Just like the polymorphism between EXOC4 and LRGUK, AHCYL2 is associated with type 2 diabetes." (PMID 27589727, 2016).
breast tumors (1 paper, 2024). "LRGUK is involved in diverse aspects of sperm assembly, including the microtubule-based shaping of spermatozoa; it was more frequently overexpressed in luminal A breast tumors." (PMID 38467851, 2024).
tumor (1 paper, 2024). "Finally, the expression pattern for the ER-related markers was more precarious, showing only a minority of tumor cells expressing either TEX14 or LRGUK, with a significant contribution of cells from the microenvironment for TEX14 expression." (PMID 38467851, 2024).
LRGUK also shares sentences with these, for which no sentence is quoted: asthenozoospermia (1 paper); deafness (1).